Y_RNA (Y RNA )
Gene: Miscellaneous RNA gene on chromosome 9 (83,992,932 to 83,993,033, forward strand). Ensembl gene ENSG00000202523.
Homologues: Orthologues: chimpanzee Y_RNA (100% identical). Paralogues in human: Y_RNA (89% identical), Y_RNA (86% identical), Y_RNA (85% identical), RNY3 (84% identical), RNY3P1 (84% identical), Y_RNA (84% identical), Y_RNA (83% identical), RNY3P11 (82% identical), RNY3P14 (82% identical), Y_RNA (82% identical), RNY3P7 (81% identical), Y_RNA (81% identical), and 94 more.